NRBP1 (nuclear receptor binding protein 1)
Description:
Required for embryonic development (By similarity). Plays a role in intestinal epithelial cell fate and proliferation, thereby involved in the architectural development of the intestine potentially via the regulation of Wnt-responsive genes (By similarity). May play a role in subcellular trafficking between the endoplasmic reticulum and Golgi apparatus through interactions with the Rho-type GTPases. Binding to the NS3 protein of dengue virus type 2 appears to subvert this activity into the alteration of the intracellular membrane structure associated with flaviviral replication.
Synonyms: BCON3; NRBP; MUDPNP; MADM
Tractability: Small molecule: it belongs to a druggable protein family. PROTAC: ubiquitination databases record sites on it; its protein half-life has been measured.
Gene: Protein-coding gene on chromosome 2 (27,427,790 to 27,442,260, forward strand). Ensembl gene ENSG00000115216.
Subcellular location: Cytoplasm, cell cortex; Endomembrane system; Cell projection, lamellipodium
Subcellular location (Human Protein Atlas): Cytosol
Pathways (Reactome):
Disease: Dengue Virus-Host Interactions
Gene expression (Transcription): Nuclear Receptor transcription pathway
Gene Ontology:
Molecular function: protein binding; protein homodimerization activity; protein serine/threonine kinase activity; ATP binding; identical protein binding; protein kinase activity
Biological process: endoplasmic reticulum to Golgi vesicle-mediated transport; DNA damage response; intracellular signal transduction; positive regulation of canonical Wnt signaling pathway; regulation of monoatomic cation transmembrane transport; epithelial cell differentiation; epithelial cell proliferation; in utero embryonic development
Cellular component: cytosol; endomembrane system; nucleoplasm; cell cortex; cytoplasm; lamellipodium; perinuclear region of cytoplasm
Genetic constraint (gnomAD): Loss-of-function variants: 10 observed, 78.83 expected, observed/expected ratio (o/e) 0.13, 90% interval 0.077 to 0.22. The upper end of that interval is the gene's LOEUF score, 0.22, which puts it in group 1 of 6, group 1 being the genes least tolerant of losing a copy. Missense variants: 344 observed, 679.72 expected, observed/expected ratio (o/e) 0.51, 90% interval 0.46 to 0.55. Synonymous variants: 233 observed, 252.35 expected, observed/expected ratio (o/e) 0.92, 90% interval 0.83 to 1.03.
Homologues: Orthologues: chimpanzee NRBP1 (100% identical), macaque NRBP1 (100% identical), pig NRBP1 (99% identical), dog NRBP1 (99% identical), rabbit NRBP1 (99% identical), guinea pig NRBP1 (99% identical), rat Nrbp1 (99% identical), mouse Nrbp1 (98% identical), tropical clawed frog nrbp1 (81% identical), zebrafish nrbp1 (81% identical), Drosophila melanogaster Madm (50% identical), Caenorhabditis elegans hpo-11 (48% identical), and 2 more. Paralogues in human: NRBP2 (57% identical), WNK2 (29% identical), WNK3 (29% identical), WNK1 (29% identical), WNK4 (27% identical), DSTYK (11% identical).
Diseases named in the same sentence as NRBP1 in open-access papers:
NRBP1 is named in the same sentence as 38 diseases in open-access papers, as found by Europe PMC text mining. Sharing a sentence is not in itself a finding about the gene and the disease. The quoted sentences say what the papers report.
prostate carcinoma (8 papers, 2015 to 2025). A carcinoma that arises from epithelial cells of the prostate gland. "For instance, in lung and breast cancers NRBP1 has been identified as a potential tumor suppressor, whereas in prostate cancer it has been implicated in tumor-promoting functions." (PMID 41430038, 2025). "More recently, studies have shown poor clinical outcomes are associated with NRBP1 over expression in prostate cancer." (PMID 26572163, 2015). "In contrast, in prostate cancer, high NRBP1 expression was linked with poor clinical outcome." (PMID 29567997, 2018). "NRBP1 is considered to be a tumor suppressor gene in several other NRBP1 cancer-related studies, such as breast cancer and lung cancer 7, 8 but is known to promote prostate cancer cell proliferation." (PMID 31413746, 2019). "Additionally, circLRP6 enhances the expression of nuclear receptor binding protein 1 by sponging miR-330-5p, which promotes the growth and metastasis of prostate cancer." (PMID 40533863, 2025). "Thus, NT8e cells harboring mutant NRBP1 was found to be consistent with its suggestive role in prostate cancer biology and other model organisms." (PMID 26572163, 2015). "However, in prostate cancer, NRBP1 was highly expressed and correlated with poor survival." (PMID 30243023, 2018).
breast cancer (7 papers, 2018 to 2025). A primary or metastatic malignant neoplasm involving the breast. "Previously, an initial investigation had documented NRBP1's suppressing effect on breast cancer cell proliferation." (PMID 39149873, 2024). "One study reported that NRBP1 negatively regulates cell proliferation in two breast cancer cell lines." (PMID 36693952, 2023). "Over the last decade, strong evidence has emerged that NRBP1 plays context-specific roles in a variety of cancers, including colorectal, lung, prostate, bladder and breast cancers." (PMID 36693952, 2023). "NRBP1 (nuclear receptor binding protein 1) acts as a tumor suppressor and is commonly downregulated in a series of cancers such as breast cancer." (PMID 30243023, 2018). "There is still ongoing discussion about the involvement of NRBP1 in breast cancer." (PMID 39149873, 2024). "However, this is contradicted by data from comprehensive functional genomic screens across cancer cell lines identifying NRBP1 as a context-specific fitness gene, specifically in breast cancer." (PMID 36693952, 2023). "In lung cancer and breast cancer, low NRBP1 is significantly correlated with poor prognosis." (PMID 29567997, 2018). "Some studies have suggested that SALL4 silencing in Dox BC resistance cell lines reverts the resistance through cell cycle arrest and downregulation of membrane transporter ABCG2, more commonly referred to as BCRP (breast cancer resistance protein) and nuclear receptor-binding protein 1 (NRBP1)." (PMID 36362083, 2022).
colorectal cancer (5 papers, 2018 to 2025). A primary or metastatic malignant neoplasm that affects the colon or rectum. "Previous studies showed that NRBP1 enhances caspase-dependent intrinsic apoptosis via JNK signaling in colorectal cancer." (PMID 41430038, 2025). "Consistently, NRBP1 upregulation in colorectal cancer (CRC) is associated with improved survival, while NRBP1 overexpression in cultured CRC cells triggers apoptosis and inhibits cell proliferation, and decreases xenograft growth in mice." (PMID 41430038, 2025). "Despite recent advances in understanding the biology of NRBP1, the role of NRBP1 and its underlying mechanism in colorectal cancer (CRC) have not been fully elucidated." (PMID 29567997, 2018). "Publications showing that NRBP1, the other member of this two-protein pseudokinase family, regulates intestinal progenitor cell proliferation, and is downregulated in a variety of human cancers, including colorectal cancers, lend support to roles for these pseudokinases in inhibiting tumor growth." (PMID 32517178, 2020).
bladder cancer (4 papers, 2019 to 2025). "For example, in prostate and bladder cancer, NRBP1 expression is positively associated with poor clinical outcomes, and silencing of NRBP1 leads to decreased proliferation, and for the latter cancer, reduced xenograft growth." (PMID 36693952, 2023). "Our findings suggest that NRBP1 is essential in the development of bladder cancer and its role as a novel diagnostic marker in BCa needs to be further investigated." (PMID 31413746, 2019). "Using the survival analysis of the TCGA database, we found that the high expression level of NRBP1 is associated with poor prognosis in bladder cancer." (PMID 31413746, 2019). "To investigate whether NRBP1 is involved in the development of bladder cancer, we used tissue microarray and analyzed the association between the expression levels of NRBP1 and clinico-pathological features of 56 patients diagnosed with bladder cancer." (PMID 31413746, 2019). "On the one hand, high levels of NRBP1 have been shown to enhance proliferation and metastasis in bladder cancer, as well as influence the oncogenic potential of triple-negative breast cancer cells via the P-Rex1/Rac1/Cdc42 pathway." (PMID 41430038, 2025). "To further illustrate the biological significance of NRBP1 in bladder cancer, we performed gene silencing of NRBP1 by siRNA." (PMID 31413746, 2019). "Subsequently, NRBP1 was silenced using siRNA in bladder cancer cell lines T24 and 5637, and cell phenotype such as proliferation and apoptosis were observed." (PMID 31413746, 2019). "We explored the potential role of NRBP1 in apoptosis of bladder cancer cells by Western blot analysis." (PMID 31413746, 2019). "Our results showed that down-regulation of NRBP1 induced the intrinsic apoptotic pathway in bladder cancer cells." (PMID 31413746, 2019). "In conclusion, our data demonstrates that NRBP1 expression is upregulated in BCa tissues and NRBP1 knockdown inhibits bladder cancer cell proliferation and promotes cell apoptosis in vitro and in vivo." (PMID 31413746, 2019). "To confirm the hypothesis that NRBP1 promotes BCa progression, we silenced NRBP1 in the bladder cancer cell lines with siRNA and observed cell proliferation and apoptosis." (PMID 31413746, 2019). "Taken together, these data suggest that NRBP1 plays a critical role in the development of bladder cancer and may represent a potential target for bladder cancer treatment." (PMID 31413746, 2019). "Transfection of two bladder cancer cell lines (T24 and 5637) with siNRBP1 significantly inhibited the proliferation and promoted intrinsic apoptosis in vitro and in vivo, demonstrating the potential anti-apoptotic role of NRBP1 in promoting proliferation of bladder cancer cells." (PMID 31413746, 2019). "Therefore, we hypothesized that NRBP1 might function as a tumor promoting gene in bladder cancer." (PMID 31413746, 2019). "The role of NRBP1 in the progression of bladder cancer has not yet been elucidated." (PMID 31413746, 2019).
gout (4 papers, 2017 to 2025). A condition characterized by painful swelling of the joints, which is caused by deposition of urate crystals. "Through comprehensive analysis of genome-wide genotype and DNA methylation data, nuclear receptor-binding protein 1 (NRBP1) was identified as a gout risk gene, with its regulatory region (72 bp upstream of the transcription start site, referred to as B1)." (PMID 41311848, 2025). "A previous GWAS study identified NRBP1 as a risk gene for gout and was shown to have elevated expression in human peripheral blood single nucleated cells from gout patients." (PMID 39734218, 2024). "In summary, we have identified a gout risk gene, NRBP1, using integrative analyses of genotype and DNA methylation." (PMID 28932319, 2017). "There results were further confirmed by in vivo bisulfite pyrosequencing showing that hypomethylation on B1 is associated with increased NRBP1 expression in gout patients." (PMID 28932319, 2017). "Here, by integrating genotype with DNA methylation, we identified a gout risk gene, nuclear receptor binding protein 1 (NRBP1)." (PMID 28932319, 2017). "In conclusion, we identified a gout risk gene, NRBP1, by integrating genome-wide genotype with DNA methylation data." (PMID 28932319, 2017). "Moreover, gout-associated increased expression of NRBP1 is regulated through methylation-dependent TFAP2A binding to the B1 region." (PMID 28932319, 2017). "The causal association of NRBP1 with gout may be weakly biased by LD (PHEIDI < 0.01)." (PMID 39734218, 2024). "In addition, NRBP1 is associated with sodium and albumin excretion and/or metabolism and may also be involved in the pathogenesis of gout." (PMID 39734218, 2024). "In our current work, we have identified and shown that NRBP1 may be a risk gene in gout." (PMID 28932319, 2017). "In addition to gout disease status, we also observed a marginal significant association between DNA methylation of B1 and serum uric acid (P value = 0.08) and a significant association between NRBP1 expression and serum uric acid (P value = 0.03)." (PMID 28932319, 2017). "Moreover, gout-associated increased NRBP1 expression is regulated through methylation-dependent TFAP2A binding to the B1 region, which might be involved in the pathogenesis of gout." (PMID 28932319, 2017). "NRBP1 inhibition plays an important role in alleviating hyperuricemia and gout by upregulating ABCG2 through the Wnt/β-catenin signaling pathway in HK-2 cells." (PMID 41311848, 2025). "At the protein level, SMR analysis revealed significant causal associations between IL2RB, NRBP1, SUMF1, and THBS3 levels and the risk of gout." (PMID 39734218, 2024). "This study identified eight potential drug-targeting genes for gout, among which NRBP1 and SUMF1 have a greater potential for development." (PMID 39734218, 2024). "SMR analysis (P < 0.05) at the protein level added emphasis on the impact of the risk genes NRBP1 and SUMF1 on gout." (PMID 39734218, 2024). "Ultimately, eight genes were identified as possible drug targets in gout, including three risk genes (ALDH3B1, NRBP1, SUMF1) and three protective genes (FCGR2B, RCE1, SLC7A7)." (PMID 39734218, 2024). "We observed elevated NRBP1 expression in human peripheral blood mononuclear cells (PBMCs) from gout patients." (PMID 28932319, 2017). "Furthermore, both normalized RNA level (gout versus control 1.425 ± 0.0656 versus 1.185 ± 0.0432 (mean ± SEM); P value = 0.004) and protein level of NRBP1 in PBMCs were found to be significantly elevated in gout patients, indicating that NRBP1 may be a gout risk gene." (PMID 28932319, 2017). "Nuclear receptor binding protein 1 (NRBP1), as a gout risk gene, and its regulatory region, 72 bp upstream of the transcription start site, designated as B1, were identified through integrative analyses of genome-wide genotype and DNA methylation data." (PMID 28932319, 2017).
gout (continued). "Considering the important role of ABCG2 in gout, it is worth further investigating the molecular mechanism of NRBP1 in gout development." (PMID 28932319, 2017). "In druggability evaluation, we found that SLC7A7 may have greater potential for gout drug development, whereas targeting NRBP1 needs to be carefully considered." (PMID 39734218, 2024). "Hypomethylation at the promoter region of NRBP1 reduces the binding of TFAP2A and thus leads to elevated NRBP1 expression, which might contribute to the development of gout." (PMID 28932319, 2017). "In order to test that increased NRBP1 expression we observed in gout patients is regulated through methylation-dependent TFAP2A binding to NRBP1 promoter region, we evaluated the DNA methylation level of the CpG dinucleotide on B1 using PBMCs of gout patients (n = 15) and healthy controls (n = 17)." (PMID 28932319, 2017). "Through experiments both in vitro and in vivo, we demonstrated that increased NRBP1 expression in gout patients may be regulated through methylation-dependent binding of TFAP2A to the B1 region, 72 bp upstream of NRBP1 transcription start site." (PMID 28932319, 2017). "NRBP1 is involved in the important process of urate homeostasis, and drug development against NRBP1 can improve uric acid excretion or inhibit renal reabsorption of uric acid, which may be a major effective way to prevent and treat gout." (PMID 39734218, 2024). "SMR analysis of DNA methylation levels and gout causal gene expression identified seven DNA methylation sites (ALDH3B1: cg18412889, cg23121335, cg25402137; IL2RB: cg25246692, cg11558856; NRBP1: cg15478930; SUMF1: (cg24840601) modifications may regulate ALDH3B1, IL2RB, NRBP1 and SUMF1 expression." (PMID 39734218, 2024). "Eight potential therapeutic targets (ALDH3B1, FCGR2B, IL2RB, NRBP1, RCE1, SLC7A7, SUMF1, THBS3) for gout were identified in the discovery cohort using MR analysis." (PMID 39734218, 2024). "However, only NRBP1 and SUMF1 were consistent with the direction of the effect of gout-producing SMR estimates at the protein and transcriptome levels." (PMID 39734218, 2024). "This study found that hypomethylation of the NRBP1 promoter region reduces the binding of NRBP1 to the transcription factor TFAP2A, which leads to elevated levels of NRBP1 and may contribute to the development of gout." (PMID 39734218, 2024). "DNA methylation increases the binding of transcription factor TFAP2A to B1, leading to suppressed gene expression; low methylation in the NRBP1 promoter region reduces TFAP2A binding, thereby increasing NRBP1 expression, which may contribute to the development of gout." (PMID 41311848, 2025).
lung carcinoma (3 papers, 2015 to 2019). "Among the novel genes identified, of genes with at least one identical mutation previously reported include a pseudokinase Nuclear receptor binding protein NRBP1 harboring heterozygous truncating mutation (Q73*) in NT8e cells, identical to as reported in lung cancer and altered in other cancers." (PMID 26572163, 2015).
hypertriglyceridemia (2 papers, 2023 to 2024). A laboratory test result indicating elevated triglyceride concentration in the blood. "We newly identified the IFT172/NRBP1 region, in the literature previously associated with hypertriglyceridemia, as involved in apolipoprotein-CIII sialylation and hypertriglyceridemia." (PMID 37834292, 2023). "At present, studies believe that the expression of the NRBP1 gene is related to apo CIII sialylation and hypertriglyceridemia." (PMID 38915894, 2024). "Moreover, we propose the NRBP1-gene as a possible player in the sialylation of apolipoprotein-CIII and hypertriglyceridemia." (PMID 37834292, 2023).
Obesity (2 papers, 2018 to 2024). Accumulation of substantial excess body fat. "The risk of obesity (BMI) is related to the NRBP1, KIF11, and KCNJ11 genes." (PMID 38915894, 2024).
type 2 diabetes (2 papers, 2018 to 2022). "Of note, based on the H4 posterior probability (H4 PP), type 2 diabetes and NRBP1 (H4 PP ≥ 0.9) shared causal variants in five tissues, while the H4 PP for SNX17 was much lower (0.483)." (PMID 35568807, 2022).
alcohol dependence (1 paper, 2026). Physical and psychological dependence on alcohol. "Epigenetic regulation was particularly evident at two methylation sites (cg07437263 and cg05102552) that indirectly influenced alcohol dependence risk by modulating CDK5R1 (63.92% mediation) and NRBP1 (95.12% mediation) expression." (PMID 42025296, 2026). "This investigation spotlights the regulatory function of DNA methylation on CDK5R1 and NRBP1 in alcohol dependence." (PMID 42025296, 2026). "Our integrative analysis identified 10 drug-targetable genes showing significant expression alterations in alcohol dependence (FDR < 0.05), with three genes (CDK5R1, CAMKK2 and NRBP1) demonstrating evidence of shared causal variants through colocalization." (PMID 42025296, 2026). "The strong mediation effects observed for CDK5R1 and NRBP1, coupled with their colocalization evidence, position these genes as promising candidates for both biomarker development and targeted therapeutic interventions in alcohol dependence." (PMID 42025296, 2026). "It implies that CDK5R1 and NRBP1 could serve as potential clinical biomarkers or therapeutic targets for the early management of alcohol dependence." (PMID 42025296, 2026).
astrocytomas (1 paper, 2024). "The incidence of high NRBP1 expression in GBM (73.5%) significantly surpasses its occurrence in pilocytic astrocytomas (15%), astrocytomas (40.6%), and oligodendrogliomas (26.6%)." (PMID 39149873, 2024).
endometriosis (1 paper, 2025). The growth of functional endometrial tissue in anatomic sites outside the uterine body. "The role of “hubs” in these endometriosis-significant interactions was performed by proteins such as FNDC4 (participates in 9 pair interactions), NRBP1 and ZNF512 (7 pair interactions each), C2orf16, GPN1, and KRTCAP3 (6 pair interactions each)." (PMID 41373783, 2025).